CD44 (CD44 molecule (IN blood group))
Diseases named in the same sentence as CD44 in open-access papers (continued):
Sharing a sentence is not in itself a finding about the gene and the disease.
ovarian carcinoma (continued). "The EOC CD117+CD44+CSCs were isolated from the human ovarian cancer cell line SKOV3 by using a magnetic-activated cell sorting system, and the lentivirus miR-200c transduced CSCs were then selected for the study." (PMID 23842108, 2013). "A recent study reported that twist-related protein 1 (TWIST1) is involved in the differentiation of ovarian CSC/TICs (type I/CD44+ cells) isolated from either ovarian ascites or ovarian cancer tissues." (PMID 23528891, 2013). "Multi-factor logistic regression analysis further confirmed that expression of Lewis y antigen and CD44, surgical stage of ovarian cancer, and size of residual lesions were all independent factors associated with chemotherapeutic resistance." (PMID 23468946, 2013). "Our assay demonstrated that human epithelial ovarian cancer CD44+CD117+cells possessed the properties of CSCs that exhibited more chemoresistance in the 3D culture than that of in 2D one." (PMID 23368632, 2013). "In spite of the lack of consensus about the markers for ovarian CSC, several groups including our own have reported the role of CD44+ ovarian cancer cells in tumor initiation and chemoresistance – a role that has been ascribed to CSC." (PMID 24403249, 2013). "CD44+ cells, including CD44+MyD88+ cells from either ascites or tumor tissues and CD44+CD24+EpCAM+ cells from ovarian cancer cell lines, exhibit the molecular phenotypes of ovarian CSC/TICs." (PMID 23528891, 2013). "In fact, although there is no consensus in the hierarchical place of CD44+ ovarian cancer cells in terms of its stemness property, there is a consensus that CD44+ ovarian cancer cells represent a more chemoresistant phenotype." (PMID 24403249, 2013). "This study has demonstrated that HA treatment reduces the ability of CBP to cause cell death and increases the expression of ABC transporters in CD44 positive ovarian cancer cell lines." (PMID 24124770, 2013). "Although the importance of HA and CD44 in ovarian cancer progression has been well established, the knowledge about their significance in mediating ovarian cancer chemoresistance is limited." (PMID 24124770, 2013). "HA increased the survival of carboplatin treated ovarian cancer cells expressing the HA receptor, CD44 (OVCAR-5 and OV-90)." (PMID 24124770, 2013). "Surface proteins such as c-Kit, CD44 and CD133 have been associated with ovarian cancer cells with stem-like phenotype." (PMID 23782518, 2013). "HA levels significantly correlate with the degree of invasiveness and metastatic potential in malignant ovarian tumors, and it promotes the attachment of cancer cells to peritoneal cells via interactions with its major surface receptor, CD44." (PMID 24124770, 2013). "CD44 surface expression is a marker for ovarian cancer stem cells, further suggesting a potential role(s) of CD44 in metastatic behavior." (PMID 23109879, 2012). "Although CD44 appears to be a promising marker in several ovarian cancer cell lines, it cannot be used solely, and other potential markers should be combined in order to characterise and isolate CSCs." (PMID 22693526, 2012). "Several studies have demonstrated that ovarian cancer cells were able to attach to peritoneal mesothelial cells by the activation of CD44 or integrin α2β1." (PMID 22330345, 2012). "Ley structures were found to be associated with CD44, and it was shown that overexpressed Ley strengthens CD44 mediated adhesion and spreading of ovarian cancer cells." (PMID 24957768, 2012). "According to published data on different ovarian cancer cell lines, there appear to be substantial variations in proportions of CD44 and CD24." (PMID 22693526, 2012). "In support of these results, another study in ovarian cancer observed great variation in CD44 and CD24 expression in almost all patients ranging from 2.2%–88.2% and 3.2%–86.7%, respectively." (PMID 22693526, 2012).
ovarian carcinoma (continued). "We previously showed, using gene expression microarray, that Ck18 expression is 7-fold higher (P = 0.0007) in CD44+/MyD88+ EOC stem cells compared to the CD44−/MyD88− mature ovarian cancer stem cells (mOCCs)." (PMID 21904548, 2011). "In this study, we focused on CD44 expression as a marker of the cancer stem cells and its evaluation is based on the percentage of ovarian cancer stem cells present in the tumor." (PMID 21904548, 2011). "It is therefore not surprising that stem cell properties have been reported in ovarian cancer cells isolated using different cell surface markers, including CD44, CD133, or CD24." (PMID 21904548, 2011). "Many studies proved the importance of CD44 and its receptors in the biological behaviors of ovarian cancer." (PMID 21294926, 2011). "For this study, we focused using a single marker and selected CD44 as a widely accepted marker for the identification of ovarian cancer stem cells." (PMID 21904548, 2011). "We show in this paper that CD44+ EOC stem cells can be detected in tumor sections obtained from patients with ovarian cancer." (PMID 21904548, 2011). "The addition of anti-CD44 antibodies has been reported to significantly decrease adhesion of ovarian cancer cells to HA." (PMID 21541039, 2011). "Our own in vitro studies have shown that HA increases the adhesion of CD44 expressing ovarian cancer cells to peritoneal cells." (PMID 21541039, 2011). "Inhibiting the expression of CD44 or blocking its binding to receptors and downstream signal molecules can inhibit the progression of ovarian cancer." (PMID 21294926, 2011). "Using ovarian cancer tissue sections from 117 patients with primary disease, we investigated the relationship between the number of CD44+ EOC stem cells and various clinical parameters, which include chemoresponse and progression-free survival." (PMID 21904548, 2011). "This article mainly found that Lewis y antigen, as a structure in CD44 molecule, strengthens CD44-mediated adhesion and spreading of ovarian cancer cells." (PMID 21294926, 2011). "This review focuses on versican, HA, and CD44 and their potential as therapeutic targets for ovarian cancer." (PMID 21541039, 2011). "Ovarian cancer cells adhere to peritoneal mesothelia via the formation of several compounds: CD44/HA, β1-integrin/fibronectin, CA125/mesothelin, and so on." (PMID 21294926, 2011). "Our most recent data also shows that motile SKOV-3 ovarian cancer cells expressing CD44 also form a HA/versican pericellular matrix." (PMID 21541039, 2011). "Overall the combined data supports a role for versican together with HA and CD44 in a number of the key steps needed for ovarian cancer metastasis." (PMID 21541039, 2011). "The peritumoral stroma surrounding ovarian cancer cells is enriched in HA, versican and CD44 all of which can promote ovarian cancer metastatic behavior." (PMID 21541039, 2011). "The dependence of CD44 for the versican and HA-mediated effects was confirmed by the inhibition of pericellular matrix formation as well as versican mediated motility and invasion of ovarian cancer cells following treatment with CD44 neutralizing antibody." (PMID 21541039, 2011). "Our results suggest that formation of a CD44/HA/versican macromolecular complex promotes the motility and invasion of ovarian cancer cells." (PMID 21541039, 2011). "Altered expression of several ECM molecules including versican, hyaluronan (HA) and CD44 have been described in ovarian cancer and impact on ovarian cancer outcome." (PMID 21541039, 2011). "In ovarian cancer cells, in vitro adhesion, invasion, and resistance to apoptosis were inhibited by CD44 siRNA." (PMID 21541039, 2011). "In ovarian cancer cells, paclitaxel-HA conjugate interacted with CD44, entered the cells through a receptor-mediated mechanism, and exerted a concentration-dependent inhibitory effect on tumor cell growth." (PMID 21541039, 2011).
ovarian carcinoma (continued). "ECM molecules including versican and hyaluronan (HA) which interacts with the HA receptor, CD44, have been shown to play critical roles in ovarian cancer metastasis." (PMID 21541039, 2011). "Ovarian cancer cell adhesion to mesothelial cell monolayers is mediated at least in part by the interaction between HA and CD44." (PMID 21541039, 2011). "Evaluation of the location of CD44+ and Ck18+ cells in tumor tissues obtained from ovarian cancer patients showed that CD44+ and Ck18+ cells are surrounded by CD44-/Ck18− mOCCS." (PMID 21904548, 2011). "We previously demonstrated that the ovarian cancer stem cells are CD44+, represent the chemoresistant population, and are able to differentiate in vitro and in vivo to CD44− cells." (PMID 21904548, 2011). "Several studies have evaluated CD44 expression in ovarian cancer tumors and correlated with survival outcome." (PMID 21904548, 2011). "It is also confirmed that the binding of CD44 to HA induces c-Src kinase activation, and is involved in the metastasis of ovarian cancer cells by activating the c-Src kinase pathway." (PMID 21294926, 2011). "Emerging evidence in ovarian cancer suggests that cells expressing CD44, CD117 or CD133 cell-surface markers have CSC properties." (PMID 21176222, 2010). "We also examined the possibility that ALDH1 is co-expressed with the CSC markers CD44, CD117 and CD133 in order to determine if ALDH1 is associated with putative stem cells in ovarian cancer." (PMID 21176222, 2010). "CD44 is a family of cell-surface glycoproteins that are expressed in a variety of human solid tumours, particularly those of gynaecological origin (e.g., ovarian cancers), and is implicated in cell adhesion, motility and metastases." (PMID 19603017, 2009). "Our group recently reported the identification and characterization of the ovarian cancer stem cells using the cell surface marker, CD44." (PMID 19619321, 2009). "A recent study showed that epithelial ovarian cancer was derived from a sub population of CD44+, CD117+ and CD133+ cells." (PMID 19014671, 2008). "In vitro binding of ovarian cancer cells to the mesothelium is only partially inhibited by anti-CD44 and anti-β-1 integrin antibodies." (PMID 17067392, 2006). "The β1 family of integrins and CD44 has been shown to mediate interactions between ovarian carcinoma cells and the mesothelial cells that line the abdominal organs." (PMID 15798771, 2005). "We evaluated the surface expression of CD44 isoforms in 22 ovarian cancer patients by means of immunohistochemistry." (PMID 8519665, 1995). "In the present study we showed that in ovarian cancer CD44 isoforms CD44v5 and CD44v6 are expressed in very low amounts by the tumours." (PMID 8519665, 1995). "In ovarian cancer, CD44 is a hyaluronic acid receptor and stimulates the EGFR-Ras-ERK pathway." (PMID 39919692, 2025). "Previous studies in fresh ovarian carcinoma samples have highlighted that OCSCs express specific markers, such as CD44, CD133, and aldehyde dehydrogenase (ALDH) activity, which are associated with stemness and may play a role in therapeutic resistance." (PMID 40699850, 2025). "Overexpression of NICD3 significantly increased the expression of CD44, a key stem cell marker, suggesting that there may be cross-talk between Notch-3 and CD44 to maintain the ovarian cancer stem cell phenotype." (PMID 40630953, 2025). "Two types of CD44+ and CD44- cells were identified in ovarian cancer studies." (PMID 38655094, 2024). "In ovarian cancer, CD44 has also been shown to be expressed in M-CSC." (PMID 39546568, 2024). "Therefore, our studies examined a clinically relevant phenomenon, in which CD44 signaling is activated in response to LMW HA that is abundant within the tumor microenvironment of ovarian cancer patients." (PMID 38796478, 2024).
ovarian carcinoma (continued). "Elevated expression of CD44 has been observed in various cancers such as prostate cancer, ovarian cancer, gallbladder cancer, oral squamous cell carcinoma and gastric cancer, demonstrating correlation with malignant biological phenotypes and an unfavorable prognosis." (PMID 38985127, 2024). "In ovarian cancer, EVs produced by tumor cells promoted peritoneal invasion through the transfer of CD44, which in turn triggered Mesothelial-to-Mesenchymal Transition (MMT) in peritoneal mesothelial cells (HPMCs) and increased secretion of MMP9 metalloproteinase." (PMID 38542421, 2024). "Moreover, an HA‐labeled PLGA nanoparticle encapsulating both paclitaxel and focal adhesion kinase siRNA was reported to bind to CD44‐positive epithelial ovarian cancer cells to overcome chemoresistance." (PMID 38783892, 2024). "Furthermore, the EV-mediated transfer of CD44 from high-metastatic ovarian cancer cells promoted migration and invasion of low-metastatic ovarian cancer cells, increasing their aggressiveness." (PMID 38542421, 2024). "In addition, we review the course of selected female malignancies, i.e., breast, cervical, endometrial, and ovarian cancer, with the main focus on the mechanisms oriented to CD44." (PMID 36830841, 2023). "Moreover, the IL-6 cytokine secreted by adipocytes plays a crucial role in the inhibition of mitochondria-triggered apoptosis in chemoresistant ovarian cancer stem cells (CSCs), particularly in the CD44+/MyD88+ cancer cell population." (PMID 38201468, 2023). "Therefore, this study aimed to retrospectively investigate the expression of ALDH1A1, CD133, and CD44 in primary epithelial ovarian cancer samples." (PMID 36768723, 2023). "Additionally, qRT-PCR analysis demonstrated significantly upregulated CD44 expression levels in ovarian cancer cell lines." (PMID 37284314, 2023). "An enforced ESRP1 expression in the ovarian cancer cell line SKOV3, significantly reduced the level of the mesenchymal cell-specific CD44 isoform 4 and increased levels of CD44 variant isoforms as well as caused overall switching from mesenchymal to epithelial phenotype of cells." (PMID 38106992, 2023). "While a study found a strong association between CD44 expression and poor prognosis, other studies presented that CD44 associated with a better prognosis whereas it is not an independent predicator prognosis biomarker of ovarian cancer." (PMID 36604635, 2023). "CD44 is a membrane protein that is highly expressed in drug-resistant ovarian cancer cells." (PMID 37400932, 2023). "The macromolecular complexes CD44/HA/versican promoted the invasion events in ovarian cancer cells." (PMID 35785191, 2022). "One possible reason for this differential uptake is that the HA coating of MOFs may specifically conjugate with the CD44 on the surface of CR SKOV-3 ovarian cancer cells." (PMID 36419626, 2022). "CD44/HA/MDR1 siRNA NPs have been successfully evaluated in ovarian cancer." (PMID 35464064, 2022). "In addition, the CD44+ fraction of ovarian cancer cells displayed higher expression of major stemness genes and NF‐κB signal genes, including RelA, RelB, and IKKα." (PMID 36226253, 2022). "It was also reported that the function of resting dendritic cells could be inhibited through GDF-15 interacting with CD44, thus facilitating ovarian cancer immune escape." (PMID 36011053, 2022). "Interestingly, a recent report showed that the downregulation of CD44 abrogated the Snail expression of ovarian cancer cells." (PMID 35682836, 2022). "Moreover, CD44, a HA receptor, is highly expressed on ovarian cancer cells, leading to CD44-mediated active targeting of tumors." (PMID 36419626, 2022). "CD44 gene knockout can increase the chemosensitivity of ovarian cancer cells to paclitaxel and inhibit tumor growth, and targeted inhibition of CD44 gene expression combined with chemotherapy drugs may be a more effective strategy for ovarian cancer treatment." (PMID 35402279, 2022).
ovarian carcinoma (continued). "It was reported that blocking CD44 gene by RNA interference (RNAi) could significantly inhibit the growth of ovarian cancer cells and the formation of tumor blood vessels and reduce the recurrence and metastasis of tumors." (PMID 35402279, 2022). "Previous studies revealed that CD44 could mediate HA-induced inhibition of miR-139-5p in ovarian cancer cells." (PMID 35350177, 2022). "In this work, we describe a novel anti-CD44 third-generation CAR directed against ovarian cancer." (PMID 34680456, 2021). "Up-regulated VCAN could also promote the invasion and movement of ovarian cancer cells by up-regulating CD44 and activating the NF-κB signaling pathway, matrix metalloproteinase 9 and hyaluronan-mediated movement receptors." (PMID 33836688, 2021). "Downregulation of CD44 expression dramatically decreased the migratory potentials and invasiveness of ovarian cancer cells in vitro and suppressed tumor growth and peritoneal dissemination of human ovarian cancer xenograft in nude mice." (PMID 34680456, 2021). "CD44 is a molecular predictor of survival in ovarian cancer." (PMID 35664989, 2021). "All of these pieces of evidence suggest that developing new strategies to target CD44 in ovarian cancer may prevent disease recurrence, metastasis, and chemoresistance." (PMID 34680456, 2021). "Additionally, a population of CD44+ CD24− ovarian cancer cells was observed and characterized by resistance to chemotherapy." (PMID 34439332, 2021). "We also conducted experiments based on the hypothesis that hyaluronan on ovarian cancer cells may bind to CD44 on peritoneal mesothelial cells." (PMID 34641504, 2021). "CD44 is highly expressed in many types of cancers including breast, prostate, and ovarian cancers." (PMID 34769230, 2021). "In addition, specific CD44+/MyD88+ epithelial ovarian cancer stem cells have been shown to be responsible for tumor initiation, even after surgical and chemotherapeutic treatment." (PMID 34439332, 2021). "Similarly, CD44+ CSCs derived from ovarian cancer patients show both upregulated glucose uptake and the expression of key genes associated with OXPHOS and FAO." (PMID 33335857, 2020). "Importantly, CD44 is known to be directly involved in peritoneal tumor implantation of ovarian cancer." (PMID 32785160, 2020). "Finally, we review the current state of therapeutic CD44 targeting and propose superior treatment possibilities for ovarian cancer." (PMID 33335857, 2020). "This study further confirms an important role for CD44 in ovarian cancer progression." (PMID 33335857, 2020). "Moreover, ovarian cancer cell adhesion has been shown to be facilitated by these changes due to increased integrin- and CD44-mediated binding sites." (PMID 33270665, 2020). "A phosphokinase array was performed to elucidate the mechanism by which PDK4-regulated stemness in ovarian cancer using ALDH+CD44+ SKOV3 cells transiently transfected with siPDK4 or control siRNA, and ImageJ analysis was applied to quantify the intensity of the spots on the arrays." (PMID 32390009, 2020). "CD44+ ovarian cancer tumors have been shown to reside near tumor stroma." (PMID 33335857, 2020). "MMP9 secretion is enhanced by exosomes secreted by ovarian cancer cells enriched for CD44." (PMID 32780245, 2020). "In addition, overexpression of CD44 in ovarian cancer cells increases their proliferation, adhesion and invasion capacity." (PMID 32423054, 2020). "Likewise, miR-3129 upregulation mediated suppression of bufalin chemoresistance in epithelial ovarian cancer via CD44 regulation." (PMID 32284792, 2020). "The ability of both CD44 and STAT3 to activate HIF-1α associated pathways may suggest their concomitant impact on glucose metabolism during ovarian cancer progression." (PMID 33335857, 2020). "Blocking of classical NF-κB pathway results in reduction of CD44+ CSCs in ovarian cancer." (PMID 31083587, 2019).